HACE1 (HECT domain and ankyrin repeat containing E3 ubiquitin protein ligase 1)
Description:
E3 ubiquitin-protein ligase involved in Golgi membrane fusion and regulation of small GTPases. Acts as a regulator of Golgi membrane dynamics during the cell cycle: recruited to Golgi membrane by Rab proteins and regulates postmitotic Golgi membrane fusion. Acts by mediating ubiquitination during mitotic Golgi disassembly, ubiquitination serving as a signal for Golgi reassembly later, after cell division. Specifically binds GTP-bound RAC1, mediating ubiquitination and subsequent degradation of active RAC1, thereby playing a role in host defense against pathogens. May also act as a transcription regulator via its interaction with RARB (By similarity).
Synonyms: KIAA1320; SPPRS
Tractability: Small molecule: a structure with a bound ligand is known. PROTAC: UniProt records ubiquitination sites on it.
Gene: Protein-coding gene on chromosome 6 (104,728,094 to 104,859,919, reverse strand). Ensembl gene ENSG00000085382.
Subcellular location: Golgi apparatus, Golgi stack membrane; Cytoplasm; Endoplasmic reticulum
Subcellular location (Human Protein Atlas): Endoplasmic reticulum; Nuclear bodies
Pathways (Reactome):
Cell-Cell communication: Activation of STAT3 by cadherin engagement
Immune System: Antigen processing: Ubiquitination & Proteasome degradation
Gene Ontology:
Molecular function: protein binding; small GTPase binding; ubiquitin-protein transferase activity; ubiquitin protein ligase activity
Biological process: Golgi organization; membrane fusion; protein K48-linked ubiquitination; protein ubiquitination; regulation of cell migration; ubiquitin-dependent protein catabolic process; Rac protein signal transduction
Cellular component: endoplasmic reticulum; Golgi membrane; nucleus; cytoplasm; Golgi cisterna membrane
Genetic constraint (gnomAD): Loss-of-function variants: 18 observed, 27.24 expected, observed/expected ratio (o/e) 0.66, 90% interval 0.46 to 0.98. The upper end of that interval is the gene's LOEUF score, 0.98, which puts it in group 4 of 6, group 1 being the genes least tolerant of losing a copy. Missense variants: 245 observed, 373.85 expected, observed/expected ratio (o/e) 0.66, 90% interval 0.59 to 0.73. Synonymous variants: 124 observed, 127.61 expected, observed/expected ratio (o/e) 0.97, 90% interval 0.84 to 1.13.
Homologues: Orthologues: chimpanzee HACE1 (99% identical), macaque HACE1 (99% identical), dog HACE1 (98% identical), mouse Hace1 (97% identical), rat Hace1 (97% identical), pig HACE1 (96% identical), guinea pig HACE1 (94% identical), tropical clawed frog hace1 (91% identical), zebrafish hace1 (86% identical). Paralogues in human: HUWE1 (28% identical), WWP1 (25% identical), ITCH (25% identical), NEDD4L (25% identical), WWP2 (24% identical), HECW1 (24% identical), NEDD4 (23% identical), HECW2 (23% identical), SMURF1 (23% identical), SMURF2 (23% identical), UBE3C (19% identical), UBR5 (18% identical), and 12 more.
Diseases named in the same sentence as HACE1 in open-access papers:
HACE1 is named in the same sentence as 62 diseases in open-access papers, as found by Europe PMC text mining. Sharing a sentence is not in itself a finding about the gene and the disease. The quoted sentences say what the papers report.
breast cancer (14 papers, 2012 to 2025). A primary or metastatic malignant neoplasm involving the breast. "For example, loss of HACE1 expression plays a critical role in mammary cell transformation and breast cancer progression." (PMID 30622235, 2019). "Up-dated versions of COSMIC and cbioportal now report mutations of HACE1 associated with breast cancer notably at position Gln-110, in the vicinity of the position Lys-111 we have pinpointed in our study." (PMID 28317937, 2017). "In contrast, HACE1 deficiency results in enhanced Rac1 signaling, contributing to breast cancer progression." (PMID 27213432, 2016). "We found that HACE1 loss in mammary epithelial cells and breast cancer leads to enhanced Rac1 signaling resulting in enhanced migration, invasion and anchorage-independent growth." (PMID 25659579, 2015). "Loss of the E3 ubiquitin ligase HACE1 results in enhanced RAC1 signaling contributing to breast cancer progression while eIF2α-mediated downregulation of RAC1 signaling attenuates malignant phenotypes of breast cancer cells." (PMID 28499439, 2017). "HACE1 is downregulated in multiple cancer types due to allelic loss or promoter methylation, such as Wilms’ tumor, gastric cancer, lymphoma, hepatocellular carcinoma, breast cancer, neuroblastoma, advanced colorectal cancer, etc.." (PMID 27213432, 2016). "Thus, underexpression of HACE1 in breast cancer can be attributed to allelic loss of the HACE1 locus." (PMID 25659579, 2015). "Therefore, the ramifications of HACE1 loss further substantiate the importance of Rac signaling in breast cancer and its role in tumor progression." (PMID 25659579, 2015). "Loss of HACE1 expression is commonly seen in clinical breast cancer data sets." (PMID 25659579, 2015). "HACE1 inhibits the progression of a variety of tumors, including breast cancer, lung cancer, prostate cancer, and osteosarcoma, by regulating the ubiquitination and proteasomal degradation of Rac1." (PMID 40948788, 2025). "HACE1 controls cell migration in different cell types through degradation of active RAC1 at NADPH oxidase complexes, including in breast cancer cells, where HACE1 inhibits cell migration and invasion by targeting active RAC1." (PMID 33603169, 2021). "HACE1 is an E3 ligase downregulated in several cancers, including gastric cancer and breast cancer, and was found to inhibit the Wnt/β-catenin pathway, thereby playing a role in suppressing tumorigenesis." (PMID 30962767, 2019). "For example, the E3 ligase HACE1 is a tumor suppressor in natural killer cell malignancies and breast cancer." (PMID 31248165, 2019). "HACE1 expression in breast cancer cell lines can attenuate the levels of activated Rac1 resulting in diminishing their clonogenic potential." (PMID 25659579, 2015). "Overexpression of HACE1 in MCF7 breast cancer cells reduced colony formation in soft agar compared with control cells." (PMID 25659579, 2015). "In summary, we performed a screen to identify genes capable of cooperating with HER2 allowing malignant transformation and identified HACE1 as a breast cancer tumor suppressor gene." (PMID 25659579, 2015). "Taken together, these data show that HACE1 is significantly decreased during the transformation from the normal to malignant state in breast cancer as well as other many other types of cancer." (PMID 25659579, 2015). "We now provide evidence that the loss of HECT and Ankyrin domain containing E3 ubiquitin ligase 1 (HACE1), an E3 ligase that tags activated Rac1 for proteosomal degradation, leads to breast cancer transformation." (PMID 25659579, 2015). "We observed that HACE1 is underexpressed in not only HER2+ breast cancers but also in all human breast cancer patients compared with normal breast epithelium." (PMID 25659579, 2015). "Molecular characterization of HACE1 in breast cancer shows that HACE1 attenuates Rac signaling in mammary epithelial cells, and that loss of HACE1 results in enhanced Rac signaling resulting in tumorigenicity." (PMID 25659579, 2015).
breast cancer (continued). "Together, these data indicate that breast cancer cells have lost HACE1 during their transformative process allowing cells to accumulate activated Rac1." (PMID 25659579, 2015). "Moreover, in breast cancer, HACE1 ubiquitinates and promotes the degradation of Rac1, then leading to impaired Rac signaling." (PMID 27213432, 2016). "Our work supports a critical role for HACE1 in breast cancer progression and identifies patients that may benefit from Rac-targeted therapies." (PMID 25659579, 2015). "Our findings demonstrate that while sustained Rac1 signaling (due to HER2 overexpression) may be a potent driver of transformation in human breast cancer, HACE1 is capable of tempering its downstream signaling ability." (PMID 25659579, 2015). "The contribution of HACE1 breast cancer biogenesis is still unclear." (PMID 34707697, 2012). "The expression level of HACE1 varies between different breast cancer cell lines." (PMID 34707697, 2012). "However, the expression of HACE1 varies in different breast cancer cell lines." (PMID 34707697, 2012). "For example, 6q21 is commonly deleted in leukemias and primary breast cancer, and also contains the region for HECT domain and Ankyrin repeat containing E3 ubiquitin-protein ligase 1 (HACE1) gene that under expressed in Wilm’s tumor." (PMID 34563049, 2021). "This was recapitulated at the protein level, whereby HACE1 increased in a time-dependent manner in hypoxia-exposed HEK293 and MCF7 breast cancer cells." (PMID 33603169, 2021). "HACE1 preferentially catalyzes polyubiquitination of GTP-bound Rac1 at Lys147 and decreases Rac1 protein levels in breast cancer cells." (PMID 31248165, 2019). "HACE1 could act as a tumor suppressor in various human malignancies, including lung cancer, HCC, breast cancer, osteosarcoma, colorectal cancer, gastric cancer, Leukemia and Wilms tumors." (PMID 34627241, 2021).
gastric cancer (11 papers, 2012 to 2025). A primary or metastatic malignant neoplasm involving the stomach. "In this study, we find that loss of HACE1 inhibits ROS synthesis under cisplatin stress, which helps the gastric cancer cells survive cisplatin treatment." (PMID 35343092, 2022). "HACE1‐mediated ubiquitylation of cyclin C sheds light on a better understanding of cisplatin‐associated resistance in gastric cancer patients." (PMID 35343092, 2022). "Our discovery suggests that depletion of HACE1, which is prevalent in gastric cancer, is one of the possible mechanisms underlying cisplatin‐associated resistance in gastric cancer patients." (PMID 35343092, 2022). "While in human gastric cancer cell lines, we found that loss of HACE1 reduced oxidative stress and promoted cisplatin resistance by preventing cyclin C‐induced mitochondrial dysfunction and ROS synthesis." (PMID 35343092, 2022). "Ubiquitylation of cyclin C by HACE1 regulates cisplatin‐associated sensitivity in gastric cancer." (PMID 35343092, 2022). "HACE1 is an indispensable tumor suppressor gene, and hypermethylation of its gene region has been found in a variety of human malignancies, including gastric cancer, colorectal cancer, liver cancer, Wilms tumor, B-cell lymphomagenesis." (PMID 40948788, 2025). "Recently, Jiang and colleagues revealed a novel mechanism of HECT domain and ankyrin repeat‐containing E3 ubiquitin‐4 protein ligase 1 (HACE1) ubiquitylation modifying cyclin C to regulate tumour cell resistance to cisplatin in gastric cancer." (PMID 35475325, 2022). "In this study, we identified that in gastric cancer, HACE1 catalyses the ubiquitylation modification of cyclin C when it translocates to cytoplasm under the stimulation by cisplatin treatment." (PMID 35343092, 2022). "In the present study, we elucidated a novel mechanism by which disorganisation of HACE1–cyclin C interaction drives gastric cancer cell resistance to cisplatin treatment by deregulating mitochondrial‐associated oxidative stress." (PMID 35343092, 2022). "The controversial role of HACE1 in gastric cancer cells, fibroblasts and mouse brain suggests that HACE1's regulation of oxidative response exists in molecular background specificity." (PMID 35343092, 2022). "Disruption of HACE1 and cyclin C interaction by CCNC deletion or site mutation mitigated the mitochondrial ROS production as well as the cisplatin‐induced apoptosis in gastric cancer cells." (PMID 35343092, 2022). "HECT domain and ankyrin repeat‐containing E3 ubiquitin‐protein ligase 1 (HACE1) is one of the well‐recognised E3 ligases that acts as a tumour suppressor in different cancers, including gastric cancer." (PMID 35343092, 2022). "HACE1 is frequently downregulated as an E3 ubiquitin ligase with tumour suppressive effects in multiple cancers including gastric cancer." (PMID 35475325, 2022). "Studies both in vitro and in vivo identified a suppressive role of HACE1 in impeding cell proliferation, migration, and inducing apoptosis through the down‐regulating Wnt/β‐catenin signaling pathway in gastric cancer." (PMID 29673126, 2018). "Apart from the discovery of a low expression level in clinical gastric cancer tissues, we also found a concordant low level of HACE1 in six gastric cancer cell lines as compared to human normal gastric tissues." (PMID 29673126, 2018). "To verify the influence of HACE1 on gastric cancer, we knocked out HACE1 in SGC7901 cells and replied the experiments above." (PMID 29673126, 2018). "The Western blot also showed a down‐regulation of HACE1 in human gastric cancer tissues as compared to the adjacent normal tissues." (PMID 29673126, 2018). "As substantially low expression of HACE1 was found in several gastric cancer cell lines, we established two cell lines stably expressing ectopic HACE1, AGS‐HACE1 and SGC7901‐HACE1, by introducing lentivirus carrying the HACE1 gene." (PMID 29673126, 2018).
gastric cancer (continued). "Taken together, this study demonstrated that HACE1 overexpression was able to suppress the tumor growth of gastric cancer in vivo." (PMID 29673126, 2018). "In this study, we also spotted a significant down‐regulation of HACE1 in gastric cancer tissues compared with their adjacent normal tissues." (PMID 29673126, 2018). "In this study, we collected clinical samples and analyzed the correlation between HACE1 expression and overall survival as well as the clinicopathological features of the gastric cancer patients." (PMID 29673126, 2018). "Altogether, these results showed that HACE1 has mere regulation on gastric cancer cell lines when deprived of its E3 ligase activity." (PMID 29673126, 2018). "HACE1's expression was found significantly lower in gastric cancer tissues compared with the adjacent normal tissues (P < 0.001)." (PMID 29673126, 2018). "The results of a poorer migration ability and a lower migrating rates in HACE1‐overexpression cells, exhibited by wound‐healing and Transwell assays, demonstrated a suppressive role of HACE1 on cell migration in gastric cancer." (PMID 29673126, 2018). "This inactive HACE1‐deltaHECT lost its suppressive regulation on gastric cancer proliferation and migration, indicating that HACE1 exerted its influence on gastric cancer through its E3 ligase activity." (PMID 29673126, 2018). "Intriguingly, several studies have revealed HACE1 was epigenetically inactive by gene methylation on its promoter in hepatocellular carcinoma 20 and colorectal cancer 5, as well as gastric cancer." (PMID 29673126, 2018). "Of these, NKX6.3 induced expression of Hace1 and Nrf2 proteins in gastric cancer cells and showed positive correlation with Hace1 and Nrf2 in the gastric cancer cohort." (PMID 28584243, 2017). "Similar research was performed in primary gastric carcinomas, and HACE1 was found frequently methylated in gastric carcinoma derived from male patients." (PMID 34707697, 2012). "Our previous study revealed that HACE1 was pravelently downregulated in gastric cancer, and its reduced protein level related to a poor prognosis, so we are interested to know whether HACE1 regualtes cisplatin resistance, thereby, affecting the prognosis." (PMID 35343092, 2022). "Thus, HACE1‐mediated ubiquitylation modification of cyclin C plays a role in regulating cell response to cisplatin treatment in gastric cancer." (PMID 35343092, 2022). "Circumventing the decline of HACE1 in early stage of carcinoma may impede the tumorigenesis and malignant process of gastric cancer." (PMID 29673126, 2018). "As HACE1 might play a suppressive role in gastric cancer, we tended to evaluate the correlation of different amounts of HACE1 expressed in cancer tissues to overall survival of these patients." (PMID 29673126, 2018). "In all, our studies unveiled a suppressive role of HACE1 in tumor growth and migration of gastric cancer, and it might help to provide novel insights into the blockage of tumorigenesis and malignant process of early stage of gastric cancer." (PMID 29673126, 2018). "However, in gastric cancer, there is little exploration about the influence of HACE1 on tumorigenesis and metastasis." (PMID 29673126, 2018). "The epigenetic disorder‐induced down‐regulation of HACE1 facilitated the tumorigenesis of gastric cancer; thus, blocking the aberrant epigenetic regulation might restore the expression of HACE1, which is a promising approach worthy of further studies." (PMID 29673126, 2018). "To explore the expression of HACE1 in gastric cancer tissues, we studied 142 pairs of clinical samples of patients with gastric cancer by the means of immunohistochemistry (IHC) and observed a distinctly decreased expression of HACE1 in cancer tissues compared with the adjacent normal tissues." (PMID 29673126, 2018). "Besides, we found that six gastric cancer cell lines exhibited low mRNA and protein level of HACE1 when compared to human normal gastric tissues." (PMID 29673126, 2018).
gastric cancer (continued). "As poor pathological differentiation renders tumor to grow faster and be more likely to develop invasive phenotype, this correlation might provide an indication that HACE1's abnormal depletion was related to tumorigenesis and malignant appearance of gastric cancer." (PMID 29673126, 2018). "It is still unclear whether HACE1 plays a crucial role in gastric cancer proliferation or migration, or whether it predicts a better prognosis or is a potential biomarker which is in favor of innovative therapeutic approaches for gastric cancer." (PMID 29673126, 2018). "The immunofluorescence staining revealed that fluorescent signals of cyclin C and HACE1 were colocalised in the cytoplasm of cultured HGC27 challenged with cisplatin (10 μM) and in the samples from two gastric cancer patients who received neoadjuvant therapy." (PMID 35343092, 2022). "And in gastric cancer patients with TNM I‐IIIa, those with lower HACE1 protein level had poorer overall survival (P = 0.025)." (PMID 29673126, 2018). "In 65 gastric cancer tissues, DNMT1 expression was significantly increased, whereas Hace1 expression was significantly reduced." (PMID 28584243, 2017). "HACE1 mediates the non-proteolytic ubiquitination of cyclin C in the cytoplasm, thereby promoting nuclear–mitochondrial translocation of cyclin C and maintaining the chemosensitivity of gastric cancer cells to cisplatin." (PMID 40948788, 2025). "In addition, the expression of NKX6.3, Hace1, Nrf2, and DNMT1 was compared between non-neoplastic gastric mucosae and gastric cancers." (PMID 28584243, 2017).